IFIT2 (interferon induced protein with tetratricopeptide repeats 2)
Diseases named in the same sentence as IFIT2 in open-access papers (continued):
Sharing a sentence is not in itself a finding about the gene and the disease.
coronary artery disease (1 paper, 2021). "The most relevant genetic variants of IFIT2 and IFIT3 linked to coronary artery disease are extensively summarized." (PMID 34884921, 2021). "IFIT2, IFIT3 and IFI44L are significantly related with myocardial infarction and coronary artery disease, according to Cardiovascular Disease Knowledge Portal Project Database (cvd.hugeamp.org)." (PMID 34884921, 2021).
endometriosis (1 paper, 2024). The growth of functional endometrial tissue in anatomic sites outside the uterine body. "In the high JUP group, we identified several downregulated genes in the PBMCs from endometriosis patients, including HBB, HBA1, HBA2, RGPD2, CH25H, LTB, IFIT2 and JUN." (PMID 39684780, 2024). "Comparison between participants without endometriosis (n = 5) and participants with endometriosis (n = 4) with high serum JUP values (>220 ng/mL) identified nine DEGs (HBB, HBA1, HBA2, and RGPD2 in CD14+ monocytes; CH25H, HBB, LTB, and KLRC1 in γδt; IFIT2 in NK-CD56bright and JUN in Treg)." (PMID 39684780, 2024).
endotoxemia (1 paper, 2020). "Finally, we identified and verified 9 key genes (Cd274, Cxcl1, Cxcl9, Icam1, Ifit2, Isg15, Stat1, Tlr2, and Usp18), and we predicted seven potential drugs for multi-organ damage in LPS-induced endotoxemia." (PMID 33330617, 2020).
inflammatory bowel disease (1 paper, 2008). A spectrum of small and large bowel inflammatory diseases of unknown etiology. "IFIT-1 (ISG56, P56) and IFIT-2 (ISG54, P54) are induced in response to type I and type II interferons, dsRNA, LPS, viral and bacterial infections and they are also found in several chronic diseases such as inflammatory bowel disease (IBD) or SLE." (PMID 19108715, 2008).
ischemia (1 paper, 2021). A hypoperfusion of the BLOOD through an organ or tissue caused by a PATHOLOGIC CONSTRICTION or obstruction of its BLOOD VESSELS, or an absence of BLOOD CIRCULATION. "Increased expression of IFIT2, IFIT3 and IFI44L, as well as the ratios of IFIT2/IFIT3 and IFI44L/IFIT3, may boost apoptosis and aggravate ischemia-induced damage." (PMID 34884921, 2021).
liver cancer (1 paper, 2023). An epithelial or non-epithelial malignant neoplasm that arises from the liver. "In a large multicenter study, patients with liver cancer were found to have low expression of IFIT1, IFIT2, and IFIT3." (PMID 38129382, 2023).
liver fibrosis (1 paper, 2025). "In this study, IFNα, IFNβ, ISG15, USP18, IFN-induced protein 44 (Ifi44), interferon-induced protein with tetratricopeptide repeat (Ifit) 1, Ifit2, IRF3, and IRF7 were significantly elevated in the CCl4-induced liver fibrosis model." (PMID 40260261, 2025).
metastatic melanoma (1 paper, 2023). A melanoma that has spread from its primary site to another anatomic site. "Indeed, a past study confirmed that IFIT2 is significantly up-expressed in patients who are not sensitive to anti-CTLA-4 therapy in metastatic melanoma, suggesting that the IFIT family may be useful for predicting the efficacy of immune checkpoint therapy." (PMID 37980495, 2023).
neuropathy (1 paper, 2024). A disorder affecting the nervous system that manifests with pain, tingling, numbness, and/or muscle weakness. "The IFN-induced protein, IFIT2, protects mice from neuropathy in both experimental models as demonstrated by the high susceptibility of Ifit2−/− mice to VSV and other neurotropic RNA viruses." (PMID 38888342, 2024).
non-small cell lung carcinoma (1 paper, 2024). A group of at least three distinct histological types of lung cancer, including non-small cell squamous cell carcinoma, adenocarcinoma, and large cell carcinoma. "We performed drug sensitivity analyses using the CellMiner database and found that AP-26113 (Brigatinib), a tyrosine kinase receptor inhibitor and antitumor drug, significantly promoted IFIT1 and IFIT2 expression for the treatment of some forms of advanced non-small cell lung carcinoma." (PMID 38737277, 2024).
osteoporosis (1 paper, 2022). A condition of reduced bone mass, with decreased cortical thickness and a decrease in the number and size of the trabeculae of cancellous bone (but normal chemical composition), resulting in increased fracture incidence. "Interferon-induced protein with tetratricopeptide repeats 2 (Ifit2) is involved in the innate immunity-mediated regulation of genes in response to interferon stimulation and is important for the fracture healing process in osteoporosis." (PMID 35742859, 2022).
pancreatic cancer (1 paper, 2015). "In addition, IFIT1 was detectable in normal pancreas and in 9 out of 11 cancer samples, while IFIT2 and IFIT5 could not be found in either normal pancreas or pancreatic cancer samples." (PMID 25650658, 2015).
parasitemia (1 paper, 2016). "C57BL/6 mice infected with N67 parasite induced a strong IFN-I response, including increased expression of genes such as Cd40, Isg15, Isg20, Ifit2, Mx1, Mx2, Ddx58, and Usp18 genes, leading to suppression of N67 parasitemia." (PMID 27716849, 2016).
respiratory infection (1 paper, 2024). "We have reported IFIT2’s protective effects against respiratory infection by Sendai virus, which presumably involved non-neuronal cells such as pulmonary epithelial cells or infiltrating immune cells." (PMID 38888342, 2024).
sarcoidosis (1 paper, 2024). Sarcoidosis is a multisystemic disorder of unknown cause characterized by the formation of immune granulomas in involved organs. "Compared to HCs, serum from patients with sarcoidosis significantly (p < 0.05) induced the expression of FCGR1B and IFIT2, whereas serum from patients with TB significantly (p < 0.05) reduced the expression of GBP1, SERPING1, and UBE2L6 compared to HCs." (PMID 39309852, 2024). "The induced expression levels of the individual genes FCGR1B, GBP1, IFIT2, SERPING1, and UBE2L6 could discriminate between patients with sarcoidosis and TB with a maximum Youden's index >0.80 and corresponding sensitivity >88 % and specificity >89 %." (PMID 39309852, 2024).
skin tumors (1 paper, 2025). "Consistently, we observed inflammatory genes, including Ifng, Stat1, Ifit2, Ifit3, Isg15, and Bst2, being highly expressed in the T cell cluster in skin tumors." (PMID 40282557, 2025).
squamous cell carcinoma (1 paper, 2011). A carcinoma arising from squamous epithelial cells. "IFIT2 inhibits migration and proliferation in squamous cell carcinoma cultures." (PMID 21226949, 2011).
systemic candidiasis (1 paper, 2018). "To determine the influence of IFIT2 during systemic candidiasis, we infected mice deficient in IFIT2 with C. albicans." (PMID 29666281, 2018). "Since IFIT2 is one of many proteins induced in response to infection and IFN, we tested the effects of IFN administration on pathogenesis driven by systemic candidiasis." (PMID 29666281, 2018).
tularemia (1 paper, 2019). Tularemia is an infection caused by the bacterium Francisella tularensis. "Changes in gene expression, including upregulation of STAT1, GBP1, and IFIT2, predicted tularemia-specific antibody responses." (PMID 31878161, 2019).
infection (174 papers, 2007 to 2026). The state of being infected such as from the introduction of a foreign agent such as serum, vaccine, antigenic substance or organism. "We and others have previously reported that IFIT2 protects mice from many neurotropic RNA viruses; indeed, Ifit2−/− mice are very susceptible to intranasal or subcutaneous infections with vesicular stomatitis virus (VSV)." (PMID 38888342, 2024). "These mice were very susceptible to infection with vesicular stomatitis virus indicating that the RNA-binding property of IFIT2 was essential for its antiviral function in vivo." (PMID 38888342, 2024). "Similar results were found in murine coronavirus infection, in which the deficiency of Ifit2 increases clinical scores and viral titers within a 7-day infection." (PMID 37515100, 2023). "Neurotropic coronavirus MHV-RSA59 infection of Ifit2-/- mice caused pronounced morbidity and mortality accompanied by rampant virus replication and spread throughout the brain." (PMID 33253295, 2020). "In our experimental system, the source of the IFN production was most likely the OBs; abundant IFN was induced there early (2 d.p.i.)after infection causing the induction of Ifit2 in wt mice." (PMID 22615570, 2012). "By contrast, no change in lipidation of LC3 was observed at either day 7 or 14 post-infection and the monocytes isolated from intestine of Ifit2-deficient mice showed a similar MHCII expression with a progressive loss of Ly6C marker when compared to that in control mice." (PMID 30559449, 2018). "We next evaluated the effect of mouse IFIT2 and IFIT3 expression on VSV-encoded protein levels during infection." (PMID 41093992, 2025). "ISG20 and Ifit2 also followed a similar pattern of expression where their levels were up-regulated upon infection but treatment with the inhibitor, BX795 resulted in a reduction in their levels." (PMID 39509467, 2024). "In the intranasal infection model, our results clearly showed that Ifit2 expression in neuronal cells is required for its protective action." (PMID 38888342, 2024). "Further research will be needed to identify the cell type that provides the IFIT2-mediated protection from foot pad infection." (PMID 38888342, 2024). "Following the methodology described in Section 2.3, we identified three genes: IFIT1 (infection-dependent), IFIT2 (infection-dependent), and ELOVL4 (time-dependent), using GLMQL-RMAS as predictors for multinomial logistic regression." (PMID 38655085, 2024). "Neutrophils, which were identified in the brain at only small relative abundance, dramatically expanded in the blood after infection and upregulated antiviral response genes, including Ddx58, Ifih1, Ifit1, Ifit2 and Isg15." (PMID 39749347, 2024). "The hierarchal STRING network demonstrated that genes of the proteins upstream of IFIT2 were also differentially expressed (DE) during early infection." (PMID 39162558, 2024). "The composition of M1 macrophages remained largely unchanged after infection with Apoe, Ifit2 and Ccl3_ macrophages being the major constituents." (PMID 39129565, 2024). "Ifit1 and Ifit2 are induced in response to dsRNA, type I and type II IFNs, and infection by various viruses." (PMID 39077737, 2024). "Knockdown of DCAF7 had a relatively minimal effect on suppression of IFI6, IFIT1, OAS1&2 while affecting IFIT2 slightly more with HAdV-B7 infection." (PMID 38940561, 2024). "Both serum IFNβ and hepatic IFNβ-dependent genes (including Ifit2, Rsad2, Iigp1 and many more of the ISGs discussed here) were over-expressed in Dusp1-/- mice following infection with E. coli." (PMID 37942320, 2023). "MX1, OAS, IFIT1, and IFIT2 showed a significantly larger induction in the WT-infection compared to the ΔUL138STOP-infection either at 24 hpi for OAS or 48 hpi for MX1, IFIT1 and IFIT2." (PMID 37289831, 2023). "Distinct from PKR and RNaseL, the Ifit2 member of the Ifit group of ISGs exerts potent anti-viral activity in the CNS following MHV-A59 infection." (PMID 38140641, 2023).
infection (continued). "IFIT1 transcript was reduced, while IFIT2 was unchanged in WT infection compared to mock-infected control as shown in our previous work." (PMID 35758691, 2022). "Before infection, the cis-element was linked to IFIT1B and IFIT5, which were dynamically reshuffled to link with IFIT1, IFIT2, and IFIT3 after infection." (PMID 36195603, 2022). "Both VSV and EMCV infections cause neuroinvasive disease and induce IFN-β, IFIT1, and IFIT2 in the brain." (PMID 36325336, 2022). "CRISPR knock-out was performed to find significant host factors in influenza virus replication in cells, and as a result of this study, it was shown that IFIT2 (an interferon-stimulated gene), which has antiviral activity, reduces infection." (PMID 35326449, 2022). "In neurotropic coronavirus MHV-RSA59 infection, IFIT2 promoted viral clearance by facilitating microglia activation and recruitment of NK1.1 and CD4 T cells to the brain." (PMID 36325336, 2022). "Genes encoding interferons (Ifnb, Ifnl2 and Ifnl3), chemokines (Ccl7, Ccl5, and Cxcl10), and ISGs (Ifit1, Ifit2, Ifit3b, Oas3, Ifi44, Rsad2, and Isg15, among others) were prominently represented among those induced by infection in Ifnar1-/- mice." (PMID 34591933, 2021). "Per bin, the intron counts of the infection-induced genes IFIT2, OAS2, CCL5, IL6, NFKBIA, and TNF are shown, along with ATXN10 as control." (PMID 33585804, 2021). "TNFAIP3, PPP1R15A, NFKBIA, and IFIT2 had shown bimodal gene expression in various immune cells from severely infected patients compared to healthy or moderate infection cases." (PMID 33602138, 2021). "As expected, IAV infection also resulted in increased expression of Ifit2, Mx1, and Oasl2 over mock infection." (PMID 33593970, 2021). "The increased expression of EGFP supports the correlation between increased viral load, accelerated disease onset and more severe disease symptoms following RSA59 infection in Ifit2-/- compared to WT mice." (PMID 33253295, 2020). "Surprisingly, microglial CX3CR1 expression was significantly lower in Ifit2-/- compared to WT mice following infection, although levels were similar in naïve mice." (PMID 33253295, 2020). "We verified a strong upregulation of CXCL2, CXCL3, IFNλ-1, -2 and IFIT-2 genes following a basolateral infection of HIBCPP with E-30 at MOI 0.7 compared to uninfected conditions." (PMID 32872518, 2020). "We used qPCR to measure the gene expression of the NF-κB–activated genes IL-8 and IL-6 as well as the interferon-stimulated genes (ISGs) IFIT1 and IFIT2 in MyD88-deficient cells and MyD88-intact cells during DENV2 infection." (PMID 32117091, 2020). "Infected kidneys from the IFIT2 KO mice showed a significant increase in levels of a majority of the chemokines relative to WT mice early in infection." (PMID 29666281, 2018). "IFIT2 KO mice receiving a bloodstream C. albicans inoculum of 2.5 × 105 CFU were better able to survive the infection." (PMID 29666281, 2018). "C. albicans increased ROS production in cells of both WT and IFIT2 KO mice; however, cells isolated from IFIT2 KO mice displayed statistically higher levels of ROS, both prior to and after infection." (PMID 29666281, 2018). "Ten days postinfection (p.i.), 95% of WT animals succumbed to infection, whereas nearly 50% of IFIT2 KO mice were alive." (PMID 29666281, 2018). "To determine if the neutrophil or macrophage population is influenced by IFIT2, we tested depletion of these phagocytic subsets during infection of WT or IFIT2 KO mice." (PMID 29666281, 2018). "Interferons (IFNs) are critical mediators of the innate defense to infection, and in this study we evaluated the contribution of a specific gene coding for IFIT2 induced by type I IFNs in a murine model of disseminated Candida albicans." (PMID 29666281, 2018). "By contrast, the upregulated IFIT1 and IFIT2 transcripts which began to rise only by 4 hours were refractory to the activity of incoming vhs and required active infection to be degraded (left-hand panel)." (PMID 30475899, 2018).
infection (continued). "The expression of Interferon stimulated genes (IFIT1 and IFIT2) also reduced with progression of infection." (PMID 27282499, 2016). "In this dataset, for example, IFIT2 expression increases 3.4 log2-fold 3 dpi and remains sustained throughout infection." (PMID 27595844, 2016). "IFIT1 binds to the free 5′-ppp moiety on RNA of a number of viruses, including influenza A virus, and inhibits infection by forming a complex with IFIT2 and IFIT3 that sequesters viral nucleic acid." (PMID 25191744, 2014). "Infection or treatment with type I IFN induces pro-apoptotic genes; IFN-stimulated gene 54 (ISG54) or IFN-induced gene with tetratricopeptide repeats 2 (IFIT2) that promotes apoptosis by mitochondrial-associated BCL2 family proteins." (PMID 24273750, 2013). "In accord with the well-established concept of IFN action, pre-induction of Ifit2 in neurons, before the onset of infection, was essential for the antiviral effect." (PMID 22615570, 2012). "The interferon-induced protein with tetratricopeptide repeats 2 gene (IFIT2) displayed an mRNA expression profile that showed a sharp decrease in PBMC at 21 dpi compared to pre-infection that was comparable for both breeds." (PMID 19409086, 2009). "Here, using a newly generated conditional knockout mouse, we report that ablation of Ifit2 expression only in neuronal cells was sufficient to render mice susceptible to neuropathogenesis caused by intranasal, but not subcutaneous, infection of VSV." (PMID 38888342, 2024). "Similar to the data from our infection experiments were IFIT2 and MxB upregulated in these pDCs." (PMID 36146793, 2022). "Furthermore, we verified the upregulation of CXCL8, CXCL2, CXCL3, IFNλ-1, -2 and IFIT-2 genes following an apical infection of HIBCPP cells with E-30 at MOI 20 compared to uninfected condition." (PMID 32872518, 2020). "However, despite the absence of IFN-β expression induction in mel Ibr and mel Z, this cell line, in turn, induced the expression of certain ISGs—MxA, TNFSF10, IFIT2 24—72 h post infection." (PMID 32033013, 2020). "Taking insights from the studies in Ifit2-/- mice at the acute stage, we can suggest that RSA59 infection in Ifit2-/- mice can be an appropriate model to study the nexus between T cells and microglia and their combined effect on host immunity and antiviral immune responses." (PMID 33253295, 2020). "Treatment of PBMCs with MA (in the absence of infection) led to the induction of IFIT2, IFIT3, and OAS genes; they are associated with categories Interferon alpha/beta Signaling (p-value = 7.25E-4) and Interferon Signaling (p-value = 7.76E-3)." (PMID 31796757, 2019). "WT and IFIT2 KO mice were treated with clodronate 24 h prior to infection with C. albicans." (PMID 29666281, 2018). "One potential hypothesis is that dysregulation of ISG induction, perhaps due to infection, could perturb the balance of IFIT2 and IFIT3, promoting cell death to restrict pathogen spread." (PMID 29554348, 2018). "Our studies show that the majority of the ~100 upregulated genes in infected HFFF cells at 4 hours were classified as ISG transcripts, with at least two of these (IFIT1 and IFIT2) shown by our more detailed studies to be activated between two and four hours after infection." (PMID 30475899, 2018). "To determine whether a specific phagocyte lineage is responsible for improved survival of IFIT2 KO mice, we depleted mice of either neutrophils or monocytes and macrophages prior to infection." (PMID 29666281, 2018). "Likewise our IFIT2 KO strain displayed a decreased survival of infection with vesicular stomatitis virus (VSV)." (PMID 29666281, 2018). "For example, in the rhAPC samples, the expression of IFIT2 increased 4 log2-fold and 7.4 log2-fold at 3 and 6 days post-infection, respectively; in the rNAPc2 samples the increases were 4.6 log2-fold and 6.9 log2-fold at 3 and 6 days post-infection, respectively." (PMID 27595844, 2016).